PON1 (paraoxonase 1)
Diseases named in the same sentence as PON1 in open-access papers (continued):
Sharing a sentence is not in itself a finding about the gene and the disease.
coronary artery disease (continued). "Also, two SNPs in the PON1 (Q192R; rs662 and L55M; rs854560) show a high risk of cardiovascular disease and a higher risk of coronary artery disease." (PMID 22938532, 2012). "Moreover, a large prospective study pointed low serum PON1 activity as an independent risk factor for coronary events in men at high risk of coronary heart disease." (PMID 22721254, 2012). "Human paraoxonase 1 (PON1) is an HDL-associated enzyme with anti-oxidant/anti-inflammatory properties that has been suggested to play an important protective role against coronary heart diseases and underlying atherogenesis." (PMID 21569287, 2011). "Additionally, given that in some populations, subjects of the RR genotype or with R-allele were shown to be at increased risk of coronary artery disease, it would be indeed very valuable to find ways of enhancement of PON1 activity, particularly in these individuals." (PMID 35889799, 2022). "Because the PON1 activity towards paraoxon is more affected by the occurrence of coronary heart disease and genetic polymorphism the observed changes in PON1 activity towards phenyl acetate may better express the pathophysiological circumstances of the cardiac surgery itself." (PMID 28376720, 2017). "To explore the hypothesis that high levels of reactive oxygen species are implicated in LVH and LV dysfunction in CKD patients, we exploited a missense mutation in the PON1 gene coding for the Q192R variant which has been functionally associated with oxidative stress and coronary heart disease." (PMID 27313824, 2016). "In order to evaluate the atheroprotective potential of PON1, we assessed the relationships among PON1-genotype, PON1-activity and risk of future coronary artery disease (CAD), in a large prospective case-control study." (PMID 19710913, 2009). "PON1 arylesterase and paraoxonase activities and PON1-192R genotype have been reported to protect from major adverse cardiovascular events in patients with coronary artery disease and chronic kidney disease." (PMID 39125665, 2024). "In our study, we did not demonstrate statistically significant associations between PON1 rs662, rs854560 and TRIB1 rs17321515, rs2954029 polymorphisms and the risk of coronary artery disease in the form of unstable angina in our population." (PMID 39062650, 2024). "Consequently, PON1 has been described as a risk factor for developing coronary artery disease (CAD)." (PMID 39408985, 2024). "The results of this study suggest associations between the PON1 rs662, rs854560 and TRIB1 rs17321515, rs2954029 polymorphisms and lipid parameters in patients with coronary artery disease." (PMID 39062650, 2024). "Results from a recent study show that PON1 arylesterase activity in people with coronary arterial disease is lower than in normal people." (PMID 38474211, 2024). "In this work, we performed a blind pilot study on the efficacy of PON1-HDL in detecting coronary artery disease with 20 clinical samples (10 each in Control and Coronary Artery Disease group) using NGEMS." (PMID 36732521, 2023). "Overall, the reduction in PON1 activity in T2D appears to be of great importance, as it has recently been reported that PON1 activity improves the prediction of severe coronary artery disease in this population." (PMID 38247481, 2023). "Observational and case–control studies have demonstrated an association between coronary heart disease (CHD) and decreased serum PON-1 activity." (PMID 36140402, 2022). "The objective of our study was to analyze the associations between type 2 diabetes and the concentration of two enzymes – myeloperoxidase and paraoxonase-1 in patients with ischemic heart disease." (PMID 36463116, 2022). "The objective of this study was to analyze the associations between two enzymes –MPO and PON-1 and type 2 diabetes (T2DM) in patients with ischemic heart disease (IHD)." (PMID 36463116, 2022).
coronary artery disease (continued). "PON1 activity was found to be the lowest in patients after acute myocardial infarction, higher in stable coronary disease, and the highest in controls." (PMID 35889799, 2022). "In China, the relationship between PON1 activity and coronary heart disease has been reported, but its relationship with AIS is still unclear." (PMID 33628379, 2021). "In numerous disease processes where increased oxidative stress was seen, serum PON1 activity decreased, e.g., dementia and Alzheimer’s disease, bronchial asthma, and coronary heart disease." (PMID 35083004, 2021). "According to Correia and Perry, the PON-1 activity is lower in patients with carotid disease, coronary disease, and myocardial infarction, and therefore, it is related to heart disease risk." (PMID 30944734, 2019). "There is general agreement in the literature that serum PON1 paraoxonase activity is decreased in patients with coronary artery disease or acute coronary syndromes, as compared to healthy individuals." (PMID 29333213, 2017). "The consequence of oxidative stress is lowering of PON1 activity as observed in the course of coronary artery disease." (PMID 28529953, 2017). "The activity of PON1 is decreased in patients with coronary artery disease, myocardial infarction or chronic kidney disease." (PMID 25155309, 2016). "The activity of PON1 was shown to be decreased in patients with coronary artery disease, myocardial infarction or chronic kidney disease." (PMID 25155309, 2016). "A recent meta-analysis, which considered 47 such studies, reported that PON1 activity was 19% lower in patients suffering from coronary heart disease than in unaffected controls." (PMID 26528181, 2015). "The study by Jayakumari and Thejaseebai found low PON-1 activity in patients with a coronary artery disease Therefore, PON-1 shows antiatherosclerotic properties." (PMID 25530760, 2014). "In recent years, authors have suggested that low PON1 activity and concentration were important determinants of the presence of coronary artery disease." (PMID 20804546, 2010). "Although serum PON1 activity in patients with coronary heart disease is decrease and is negatively related to the severity of coronary artery lesions, the correlation between PON1 activity and CIMT is controversial." (PMID 20804546, 2010). "However, the results of this study indicate an association between the PON1 rs662, rs854560 and TRIB1 rs17321515, rs2954029 polymorphisms with lipid parameters in patients with coronary artery disease." (PMID 39062650, 2024). "The purpose of the present study was to evaluate the association of the PON1 rs662, rs854560 and TRIB1 rs17321515, rs2954029 gene polymorphisms with the risk of coronary artery disease in the form of unstable angina and to investigate their association with biochemical parameters in these patients." (PMID 39062650, 2024). "PON1 rs622 AA genotype was also associated with increased risk of coronary artery disease (CAD) as opposed to PON1 rs854560 TT genotype which was associated with decreased risk." (PMID 38084238, 2023). "The presented study shows some of the possible directions for future research to bring us closer to the full understanding of the dysfunctional high-density lipoprotein and the role of myeloperoxidase (MPO) and paraoxonase-1 (PON-1) in patients with ischemic heart disease and type 2 diabetes." (PMID 36463116, 2022). "Similarly, several studies revealed low activity of PON1 in patients with coronary artery disease, ischemia, acute coronary syndrome and coronary occlusion." (PMID 35453382, 2022). "In the group of female patients with coronary heart disease and in the control group of healthy women genetic variations including the PON1 promoter (-107 C/T, -162 G/A, -831 G/A) and coding region (160 R/G, 192 Q/R,) as well as PON2 311 S/C, and PON3 -133 C/A polymorphisms were evaluated." (PMID 33670025, 2021).
coronary artery disease (continued). "The possible relationship between variations in PON1 promoter region and coronary heart disease and a potential usefulness of these variations as a predicting factor remains unclear, although some studies seemed to be exceedingly promising." (PMID 33670025, 2021). "Similarly, ozone therapy significantly improved PON-1 activity in HDL from coronary artery disease patients who were experiencing a decrease in lipid-peroxidation and LDL-oxidation." (PMID 34829522, 2021). "Moreover, HDL from coronary disease patients has decreased PON-1 activity compared with that from healthy controls." (PMID 31052559, 2019). "Recent studies show that there is a specific interaction between MPO, apoAI, and PON1 on the surface of HDL and that the MPO/PON1 ratio could be a potential indicator of dysfunctional HDL and, thus, be used for risk stratification in coronary artery disease." (PMID 28611100, 2017). "Neither Q192R nor M55L PON1 gene polymorphism was associated with increased coronary artery disease incidence." (PMID 27213056, 2016). "The major finding of our study is the demonstration of decreased activity of PON-1 and increased concentration of 8-iso-prostaglandin F2 in patients with coronary artery disease (CAD) proved by angiography and establishment of the correlation between these factors and the severity of CAD." (PMID 26697134, 2015). "Although PON1 activity is inversely associated to the incidence of coronary artery disease, there is no data on the behavior of PON1 during different stages of HC." (PMID 22721254, 2012). "Moreover, when other antioxidant-related gene polymorphisms (SOD2, SOD3, PON1, and GSTT1) are present, GPX3 rs3828599 is more strongly associated with the incidence of hypertension and is positively associated with coronary artery disease and with the severity of coronary atherosclerosis." (PMID 41152890, 2025). "However, the EPIC-Norfolk prospective population study found that the PON1 genotype and activity did not predict the risk of future coronary artery disease." (PMID 39125665, 2024). "Moreover, the low PON1 activity was inversely related to the severity of coronary artery disease." (PMID 35453382, 2022). "In addition, PON1 has a protective role in coronary artery disease and ischemic stroke." (PMID 32917272, 2020). "Additionally, patients with coronary artery disease (CAD) present lower serum PON1 activity." (PMID 27213056, 2016). "Nevertheless, in patients with coronary heart disease(CHD) and age-matched controls, a highly significant positive correlation between both PON1 activities and concentrations and HDL-cholesterol and apoA-I level was found." (PMID 33670025, 2021). "In the past few years, the Paraoxonase multigene family (PON1, PON2, PON3) has been shown to play an important role in pathogenesis of cardiovascular disorders including coronary artery disease (CAD)." (PMID 31816846, 2019). "Analysis of HDL particles from patients with coronary artery disease (CAD) patients revealed an enrichment of APOE, APOC-IV, PON-1, complement C3 and APOA-IV in HDL particles when compared to healthy controls." (PMID 29527140, 2018). "Fenofibrate increased PON1 activity in people with high levels of cholesterol and ischemic heart disease, while bezafibrate and gemfibrozil for 8 weeks did not have a direct effect on PON1." (PMID 38474211, 2024). "Unlike the control group, coronary heart disease patients showed lower PON1 levels and paraoxonase activity, independently to the studied polymorphism genotype (p < 0.001)." (PMID 36118876, 2022).
coronary artery disease (continued). "Therefore, studies are needed to determine the specific lysine residues of PON1 modified by IsoLG when added in vitro, the effect of these modification on PON1 structure, and whether these same modifications are increased for PON1 isolated from individuals with coronary artery disease." (PMID 34331945, 2021). "In conclusion, the present study supports the theory that the effect of 12 months of simvastatin treatment on PON1 activity and urine 8-isoprostanes is not significant in patients with stable coronary artery disease." (PMID 27213056, 2016). "Other prospective studies expanded on the negative correlation between PON1 activity and coronary heart disease by also reporting circulating levels of lipid peroxidation products, linking these to PON1 anti-oxidative activity." (PMID 26528181, 2015). "Different PON1 activities have been assessed in 293 subjects with (n = 88) or without MS (n = 205) and with (n = 195) or without (n = 98) angiographically proven coronary artery disease (CAD)." (PMID 21960992, 2012). "Several negative relationships were observed between serum PON-1 activity and carotid IMT in subjects with coronary heart disease, hypertension, and ankylosing spondylitis." (PMID 32214403, 2020). "Similarly, a negative relationship was observed between PON1 activity and IMT in individuals with coronary heart disease." (PMID 32214403, 2020).
dyslipidemia (82 papers, 2009 to 2026). "To conclude, this study demonstrated a compelling association between decreasing levels of TETRA and PON1 and increasing severity of heart failure in patients with hypertension and dyslipidemia." (PMID 40422267, 2025). "Although dyslipidemia seems to be associated with the risk of development of hypertension, and affects PON1 activity in CKD, there are sparse data on PON1 activity levels in patients with hypertensive nephropathy." (PMID 38982880, 2024). "We have shown significant small nerve fibre damage in participants with severe obesity which was associated with reduced PON-1 activity, higher serum triglycerides and metabolic syndrome." (PMID 34131170, 2021). "Arthritis activity in K/BxN mice was associated with a marked dyslipidemia, lower PON1 activity and higher bioactive lipid mediators (BLM), as well as a dysregulated hepatic lipid gene expression profile." (PMID 33033318, 2020). "Specifically, this association improved hyperglycemia, dyslipidemia, and oxidative stress, increasing the activity of the antioxidant enzyme paraoxonase 1 (PON1), in diabetic rats." (PMID 33080891, 2020). "ARE activity has been linked to the paraoxonase-1 gene which has roles in lipoprotein oxidative damage prevention and being protective against metabolic syndrome." (PMID 31698676, 2019). "For example, loss of ARE and PON1 is associated with metabolic syndrome and are considered independent risk factors for cardiovascular disease." (PMID 31010095, 2019). "In the ROC curve for PON-1, PON-1 prediction values < 180 U/L were associated with the diagnosis of metabolic syndrome with a sensitivity of 97.8%, a specificity of 95.5%, (area under the curve: 0.97; 95% confidence interval: 0.91–1.00; P < 0.001)." (PMID 25530760, 2014). "And a stronger association between decreased serum PON1 activity and metabolic syndrome was found in childhood obesity when TBBL was used as substrate compared to paraoxon." (PMID 24666514, 2014). "PON1 SNP rs662 may have a role in metabolic syndrome, and those carrying its variants may exhibit reduced levels of PON1 activity and few responses to pharmacotherapy." (PMID 36014826, 2022). "The DNA methylation of CpG4 in the PON1 promoter would lead to a low expression of PON1 mRNA, which might induce clopidogrel resistance in the patients with dyslipidemia, and the number of stents might be a risk for CR." (PMID 30891852, 2019). "HDL-associated enzymes including PON1 become dysfunctional and/or depleted under these conditions, as well as under inflammatory conditions, and metabolic diseases such as type 1 and type 2 diabetes, metabolic syndrome (MetS), and premature CVD." (PMID 19922610, 2009). "However, in another study including patients with dyslipidemia, the higher DNA methylation level of four CpG dinucleotides in the PON1 promoter region was associated with poorer clopidogrel response, which according to authors resulted from the lower expression of PON1 mRNA." (PMID 33670025, 2021). "Previously, we had shown that patients with metabolic syndrome have increased PON1 activity after an exercise training program performed over 12 weeks." (PMID 38068730, 2023). "Nevertheless, modifications in PON1 were unaffected by the presence of hyperglycemia, dyslipidemia, or metabolic syndrome or the administration of statins." (PMID 38136158, 2023). "Aqueous extracts of yerba mate, which has a high concentration of polyphenols, can contribute to the improvement of PON1 levels in individuals affected by overweight or obesity and dyslipidemia." (PMID 35889799, 2022). "An inverse association between methylation levels of PON1 promoter region CpG sites and ARE in adults with metabolic syndrome was described in a six-month energy-restricted dietary weight-loss intervention." (PMID 35889799, 2022). "Low activity of PON1 and high levels of lipid peroxides were measured in patients with metabolic syndrome." (PMID 35889799, 2022).